CD55 (CD55 molecule (Cromer blood group))
Diseases named in the same sentence as CD55 in open-access papers (continued):
Sharing a sentence is not in itself a finding about the gene and the disease.
Arthritis (13 papers, 2011 to 2025). Inflammation of a joint. "We concluded that CD55 on both immune and stromal cells is contributing to protection against immune complex-mediated arthritis in susceptible mice." (PMID 25596646, 2015). "Consistent with our previous research, CD55 gene expression was nearly 4-fold lower in arthritis-derived HSE synovial fibroblasts compared to K4IM cells, further highlighting the protective role of PEMF stimulation." (PMID 39063955, 2024). "In humans, studies have confirmed that CD248 and PPDN (together with FAP and DAF/CD55) are highly expressed in the synovial tissue in the early stage of arthritis." (PMID 37298499, 2023). "Synovial tissue expression of stromal markers in early arthritis was analyzed using immunofluorescence to detect stromal markers CD55, CD248, fibroblast activation protein and podoplanin." (PMID 30847027, 2019). "Applying in-depth analysis of synovial tissue, three-dimensional FLS micromasses, and the K/BxN serum-induced experimental model of arthritis, we here explored the basis and the consequences of the enhanced presence of CD55 in the intimal lining layer." (PMID 25596646, 2015). "To explore the role of stromal CD55 in arthritis development, as an extrapolation to human CD55, abundantly expressed by FLS, we generated bone marrow chimeric mice expressing CD55 on either immune or non-immune cells." (PMID 25596646, 2015). "To address the possibility that CD55 protects the synovial tissue from complement-mediated immune activation in vivo, we studied the K/BxN serum transfer model of arthritis." (PMID 25596646, 2015). "CD55 is an established histological marker for FLS in the intimal lining layer of the synovium in arthritis patients." (PMID 22590509, 2012). "We studied the expression levels of CD55 on FLS from patients with different forms of arthritis by flow-cytometric analysis." (PMID 22590509, 2012). "Interestingly, a study by Hoek found that deletion of CD55 improved arthritis symptoms in mouse models." (PMID 39928679, 2025). "In our study, we found a lowered CD55 gene expression in HSE compared to K4IM, where we could also suggest a reduced CD55 related protection of the cells against arthritis." (PMID 36294967, 2022). "CD55 deficiency did not enhance K/BxN serum-induced arthritis, but further exaggerated disease activity in Fcgr2b−/− mice." (PMID 25596646, 2015). "Moreover, this study helps clarify the roles of CD55 in the pathogenesis of arthritis by demonstrating involvement in the protection against immune complex-mediated K/BxN serum transfer arthritis in susceptible mice lacking the inhibitory FcγRIIB." (PMID 25596646, 2015). "As growing evidence suggests that CD55 is part of the stromal address code that directs the retention and survival of inflammatory immune cells in the synovium, it will be important to study the expression of CD55 in early arthritis and in various forms of established arthritis." (PMID 22590509, 2012). "Stromal cell markers CD55, CD248, FAP and podoplanin are expressed in the earliest stage of arthritis." (PMID 30847027, 2019). "Stromal cell markers CD55, CD248, FAP and podoplanin are expressed in ST in the earliest stage of arthritis." (PMID 28793332, 2017). "Possibly related to the interaction of CD55 with CD97, we found amelioration of collagen-induced arthritis and a trend toward less severe K/BxN serum transfer arthritis in mice that lack CD55 or CD97." (PMID 25596646, 2015). "ST from 56 patients included in two different early arthritis cohorts and 7 non-inflammatory controls was analysed using immunofluorescence to detect stromal markers CD55, CD248, fibroblast activation protein (FAP) and podoplanin." (PMID 28793332, 2017). "We demonstrate deposition of CD55 on a collagen fiber network that compacts the FLS and describe a supportive role of CD55 in protection from immune complex-mediated K/BxN serum transfer arthritis." (PMID 25596646, 2015).
Arthritis (continued). "Nevertheless, in different settings of this model, studied here and previously by our group, deletion of CD55 did not aggravate arthritis activity." (PMID 25596646, 2015). "While a previous study has suggested that the deposition of CD55 on the synovium provides protection against immune complex-mediated arthritis, our current investigation did not establish a direct correlation between the proportion of ENTPD1−CD55+ cells and radiographic OA or pain scores." (PMID 38612896, 2024). "In this setting, mice lacking CD55, like wild-type mice, did not develop arthritis." (PMID 25596646, 2015). "Thus, combined absence of FcγRIIB receptor and CD55 deteriorates K/BxN serum-induced arthritis." (PMID 25596646, 2015). "CD55 and chondroitin sulphate have been described as ligands for CD97 leading to leukocyte activation: lack of CD55 and CD97 resulted in decreased arthritis in mouse experimental models of rheumatoid arthritis." (PMID 23009096, 2012).
malaria (13 papers, 2008 to 2025). Malaria is a serious and sometimes fatal disease caused by a parasite that commonly infects a certain type of mosquito which feeds on humans. "Attempts to find a link between severe malaria outcomes and CD55 or basigin associated SNPs have so far failed." (PMID 33031369, 2020). "In a recent report, the cellular receptor CD55 was identified as a molecule essential for the invasion of human erythrocytes by Plasmodium falciparum, the causal agent of the most severe form of malaria." (PMID 28104671, 2017). "It is suggested that the loss of CD55 during malaria compromises the complement regulatory function thereby allows the deposition of opsonin C3b on RBC leading to increased erythrophagocytosis and anaemia." (PMID 22206234, 2011). "A process resembling transfer reaction of CR1 has been proposed to explain the loss of CD55 on RBC during malaria." (PMID 22206234, 2011). "Our study highlights that the loss of CRPs in both species of malaria is particularly apparent in uninfected RBCs, whereas infected RBCs of both P. falciparum and P. vivax malaria have higher expression of CR1, CD55, and CD59 than uninfected RBCs." (PMID 30429373, 2018). "CD55, a surface molecule on human red blood cells (RBCs), was recently identified as an essential receptor for the invasion of human RBCs by malaria parasites." (PMID 28104671, 2017). "Alterations of CD55 protein have been reported in a malaria mouse model that leads to complement-mediated lysis of resistant erythrocytes." (PMID 24086391, 2013). "The variables that most strongly influenced the %C3b-positive red cells were age, malaria status, and red cell CD55 level." (PMID 18717995, 2008). "In the unadjusted analysis, CR1 and CD55 were more influential than malaria status, parasite density, or IC binding capacity both in the global and in the subgroup analyses." (PMID 18717995, 2008). "For the C3b analysis, terms for age groups, red cell CR1, IC binding capacity, malaria status (included for all the samples only), parasite density at enrollment, and red cell CD55 were used as independent variables." (PMID 18717995, 2008). "After adjustment for all the confounding effects, malaria status and CD55 made the most significant contribution after age when all the samples were included, while CR1 showed a trend towards significance (P = 0.07)." (PMID 18717995, 2008). "As clinical malaria is primarily a disease of mature, peripheral blood erythrocytes, our results showing that terminal red cell maturation modifies the requirement for CD55 during invasion highlights the potential drawbacks of using cell lines to study host factors for P. falciparum." (PMID 34028351, 2021). "As the requirement for CD55 is strain-transcendent, these results suggest that CD55 or its interacting partners may hold potential as therapeutic targets for malaria." (PMID 34028351, 2021). "Moreover, CD55 has been discussed as a potential drug target and, as such, information on the degree of sequence conservation among malaria-exposed populations is crucial." (PMID 28104671, 2017). "Of note, a lack of association in the Ghanaian study group with the analyzed CD55 variants does not exclude significant associations with the same variants in other populations exposed to malaria." (PMID 28104671, 2017). "Although overall unadjusted changes in CR1, CD55, and IC binding capacity across age groups were statistically significant, only a limited number of comparisons were statistically significant after adjustment for malaria status and parasite density." (PMID 18717995, 2008). "Given the complexity of P. falciparum invasion and the unique and essential role of CD55 relative to other established receptors, targeting its activity or interaction partners in novel intervention strategies may enhance the effectiveness of future therapies or vaccines for malaria." (PMID 34028351, 2021).
malaria (continued). "The reduced expression of CR1 and CD55 on RBCs in severe anemia from both P. falciparum or P. vivax supports the hypothesis that RBCs with lower expression of CRPs are associated with RBC destruction and that this is a species-transcending mechanism of malaria anemia." (PMID 30429373, 2018). "Apparently, this is the first study to show variations in CD55 and CD59 levels in relation to RBC age during malaria." (PMID 22206234, 2011). "Increasing malaria prevalence among children >6 to ≤ 36 months of age in western Kenya, together with low red cell CR1 and CD55 levels, results in increased C3b deposition on red cells and low hemoglobin." (PMID 18717995, 2008). "Among children ≤ 24 months of age the %C3b-positive red cells was usually higher in individuals who were treated for malaria than in uninfected individuals with similarly low red cell CR1 and CD55." (PMID 18717995, 2008). "Overall levels of CD55 but not CD59 were higher in the healthy controls than in other groups but this difference was only significant for the anaemic malaria cases." (PMID 22206234, 2011). "In the adjusted analysis, in addition to age, red cell CR1, %C3b-positive red cells, and CD55 made a significant contribution to the hemoglobin level using all the samples and the samples from individuals who were negative for malaria." (PMID 18717995, 2008). "Lastly, in the adjusted analysis of samples from malaria-negative individuals, CD55 and IC binding capacity made the strongest contribution after age." (PMID 18717995, 2008). "This could be explained by the fact that CD55 seemed to be more important in preventing C3b deposition in malaria-negative individuals, who were more numerous in the study group." (PMID 18717995, 2008). "That is, during intravascular hemolysis in untreated PNH, the non‐PNH E (normal levels of CD55 and CD59) are not C3b‐opsonized as is the case for np‐E in malaria." (PMID 41230021, 2025). "Although levels of other surface molecules are known to vary as RBC age, changes in the CD55 and CD59 levels in relation to cell aging during malaria have not been examined." (PMID 22206234, 2011). "CD55 levels correlated significantly with the level of haemoglobin in anaemic (Spearman rank test: young RBC, r = 0.506, P = 0.001; mature RBC, r = 0.421, P = 0.0063; old RBC, r = 0.526, P = 0.0008; very old RBC, r = 0.375, P = 0.0246) but not in non-anaemic children with malaria." (PMID 22206234, 2011).
anemia (12 papers, 2007 to 2024). A reduction in the number of red blood cells, the amount of hemoglobin, and/or the volume of packed red blood cells. "The extent of CD55 loss from RBC of all ages early in the course of malarial anaemia and the correlation of CD55 with haemoglobin levels support the hypothesis that CD55 may play a causal role in this disorder." (PMID 22206234, 2011). "For example, a study on severe anaemia showed elevated surface IgG and immune complexes and deficiencies in the complement regulatory proteins CR1 and CD55." (PMID 36183114, 2022). "Like in the before mentioned anemias, differential expression of CD55 and CD59 on erythrocytes was also found in sickle cell disease patients." (PMID 33362763, 2020). "Significant reductions of CR1 and CD55 have largely been reported in patients with severe anaemia from Plasmodium falciparum infection, and more recently from Plasmodium vivax infection." (PMID 31533836, 2019). "One study also showed reduction of CD55 in anaemic children with haemoglobin < 10 g/L, which includes mild and severe anaemia cases." (PMID 31533836, 2019). "Expression of RBC CR1 and CD55 differed significantly among patients with different degrees of anemia." (PMID 30429373, 2018). "The correlation between CD55 and haemoglobin as observed in this study suggests that CD55 depletion contribute to RBC loss during malarial anaemia." (PMID 22206234, 2011). "The lowest expression of CR1 and CD55 was seen in patients with severe anemia." (PMID 30429373, 2018). "Levels of CR1 and CD55 were reduced in severe anemia in both falciparum and vivax malaria." (PMID 30429373, 2018). "Consistent with this hypothesis, we have found that red cells of children with P. falciparum infection and severe anemia have acquired deficiencies in CR1 and CD55, and increased C3b deposition." (PMID 18717995, 2008). "Other investigations have also implicated reduced anaemia (mild to moderate) in children with HbAS genotype relative to HbAA genotype and suggested that high levels of RBC complement regulatory proteins (CR1 and CD55) play a role in the pathogenesis of severe anaemia in malaria infection." (PMID 33827455, 2021). "In our case, where CD55 and CD59 testing is unavailable, the diagnosis depended solely on clinical evaluation, including typical symptoms like hemoglobinuria and anemia, and excluding bone marrow disease through biopsy." (PMID 39104998, 2024). "In patients with severe anemia, the expression of CR1 on uninfected RBCs between P. vivax and P. falciparum was similar; however, the expression of CD55 in P. falciparum malaria was significantly lower than that in P. vivax malaria." (PMID 30429373, 2018). "To understand the age predilection of severe anemia during P. falciparum infection, we have studied the relationship between red cell CR1 and CD55 and age." (PMID 18717995, 2008). "With decreased or a lack of CD55 and CD59 expression on their membranes, PNH red blood cells become susceptible to complement-mediated hemolysis (symptoms of which include anemia, dysphagia, abdominal pain, and fatigue), leading to thrombosis." (PMID 39273426, 2024).
colon carcinoma (11 papers, 1992 to 2025). "In conclusion, the expression of CD55 in colon cancer was associated with the genetic regulation of TFCP2, NF-κB, epigenetic regulation of miR-27a-3p, and methylation modification." (PMID 36741376, 2022). "The genes associated with CD55 are probably involved in immune-related pathways in colon cancer." (PMID 36741376, 2022). "Epidermal growth factor can induce CD55 mRNA and protein expression in HT-29 colon cancer cells through the p42/44 MAPK pathway." (PMID 40596619, 2025). "Epidermal growth factor can induce CD55 expression in colon cancer cells through the p42/44 MAPK pathway." (PMID 40596619, 2025). "Using the SurvivalMeth program, we found that the promoter region of CD55 does have hypermethylation sites in colon cancer tissues." (PMID 36741376, 2022). "The PPI network showed that CD55 and the key complement system components C3, C4A, and C4B are closely related to colon cancer." (PMID 36741376, 2022). "This study aims to evaluate the expression of CD55 in colon cancer and discover how it is regulated by transcriptional factors and miRNA." (PMID 36741376, 2022). "Several studies have shown successful usage of neutralizing CD55 or CD59 antibodies in colon cancer or NSCLC, but these were investigated in cell lines or in mouse xenograft models." (PMID 33362763, 2020). "DAF(CD55) was expressed in various intensities on almost all tumour cells of the colon carcinoma cell line HT29." (PMID 1384641, 1992). "Dho and his colleagues found that CD55 was over-expressed in metastatic colon cancer tissues, and inhibition of CD55 could restrain colon cancer tumorigenesis and metastasis." (PMID 36741376, 2022). "Since CD55 might be used as a prognostic indicator and a therapeutic target in colon cancer, we investigated the possible mechanism of the regulation of CD55 in colon cancer and its impact on the molecular and immunological characteristics of colon cancer." (PMID 36741376, 2022). "Furthermore, the DAF/CD55 was selected to be a potential biomarker for poor prognosis in patients with colon cancer, where tumors that express CD55 showed an increase in the CDC resistance." (PMID 35173724, 2022). "We speculated that CFP and CD55 might be involved in the immune infiltration of tumor cells in colon cancer." (PMID 36741376, 2022). "The high expression of CD55 has a significantly decreased 7-year survival rate for colon cancer." (PMID 36741376, 2022). "CD55 plays an important role in the development of colon cancer." (PMID 36741376, 2022). "In colon cancer, CD55 serves as a marker of tumor aggression correlated with poor 7-year survival." (PMID 33614473, 2020). "This therapeutic effect suggests a clinical relevance for CD55 in colon cancer." (PMID 33362763, 2020). "It is reasonable to speculate that miR-27a-3p affects colon cancer cells by targeting CD55." (PMID 36741376, 2022). "CD55 may serve as an indicator on the survival prognosis of patients with colon cancer." (PMID 33614473, 2020). "CD55 may be a potential biomarker for a poor prognosis in patients with colon cancer." (PMID 33614473, 2020). "Comprehensive bioinformatics analysis has also shown that CD55 was positively correlated with infiltration levels of CD8+ T cells, neutrophils, and dendritic cells in colon cancer, suggesting its potential role in tumor immune regulation." (PMID 36741376, 2022). "It has been shown that expression levels of membrane-bound complement regulatory proteins (mCRPs), including CD46, CD55 and CD59, are considerably higher in colon cancer tissues than in normal neighboring normal colon tissues." (PMID 36612172, 2022). "Our results indicated that CD55 is regulated by TFCP2, NF-κB, miR-27a-3p, and several immune-related genes, which in turn affects colon cancer." (PMID 36741376, 2022). "In two colon cancer cohorts, an increased expression level of DAF (CD55) has statistically significant correlation with poor disease-free survival (DFS)." (PMID 33614473, 2020).
colon carcinoma (continued). "Furthermore, an analysis based on TNM staging showed that the expression of CD55 and CD59 is higher in stage III and stage IV colon cancers than in stage I and stage II tumors." (PMID 36612172, 2022). "Although no complement regulator polymorphisms for risk of colon cancer have been identified, CD46, CD55, and CD59 were all upregulated in colon cancer compared to adjacent healthy tissue, with CD55 and CD59 expression correlating with tumor stage and differentiation level." (PMID 33362763, 2020). "While CD46 was found to have no clinical relevance, levels of CD55 and CD59, other complement inhibitor membrane cofactor proteins, were positively correlated with the differentiation and tumor stage in colon cancers." (PMID 27203670, 2016).